ALB (albumin)
Diseases named in the same sentence as ALB in open-access papers (continued):
Sharing a sentence is not in itself a finding about the gene and the disease.
tumor (continued). "Compared with traditional solvent-based paclitaxel, albumin-bound paclitaxel(ABP) combines hydrophobic paclitaxel and human serum albumin carrier, which decomposes more readily in the body and effectively transports paclitaxel to tumor tissues via endocytosis." (PMID 35690772, 2022). "Cyst fluid concentrations of growth hormone, testosterone, SHBG, and albumin correlated with tumor volume." (PMID 35659255, 2022). "Subgroup analyses for study location, sample size, tumor type and albumin cut-off were demonstrated consistent results." (PMID 36533070, 2022). "And then, oxidative stress will promote damage to the cell structure including proteins, lipids, membranes and DNA, it promotes tumour progression and further decreases levels of antioxidants such as serum ALB." (PMID 36531036, 2022). "In vivo, a therapeutic regimen containing albumin-bound nanoparticle (Nab)-PTX overcomes drug resistance resulting in delayed tumor growth, impaired organization of the tumor vasculature, and reduced glucose uptake." (PMID 35251961, 2022). "Albumin accumulates in the tumour due to the leaky vasculature present in the tumour tissue and is known that cancer cells take up plasma proteins in a higher rate than normal cells and utilise their degradation products for proliferation." (PMID 36005826, 2022). "ABP, a new preparation bound to human albumin, has stronger anti-tumor ability and less toxic effects compared with traditional paclitaxel preparations." (PMID 35690772, 2022). "At the pre-SIRT stage, the selected patient undergoes a catheter angiogram to scrutinize the arterial supply of the targeted tumor(s), followed by radionuclide mapping using Technetium-99m macroaggregated albumin (99mTc-MAA)." (PMID 36364476, 2022). "Previous studies have shown that in some patients with grade 2 albumin-bilirubin at baseline, a decrease in tumor burden in response to treatment leads to an improvement in liver function." (PMID 35251977, 2022). "Some pan-cancer research has indicated that tumor cells activate albumin metabolism and incur increasing albumin levels despite other studies confirming that low expressions of HDL and ALB expressions are risk factors for patients’ survival." (PMID 36135078, 2022). "The nomogram for OS, formulated based on the statistically significant factors from the multivariate analysis, showed that N stage was the strongest predictor, followed by preoperative albumin level and tumor morphology." (PMID 34778364, 2021). "In order to observe the true effect of albumin half-life extension on tumour growth we have developed the first immunodeficient version of the AlbuMus model." (PMID 33686177, 2021). "High permeability of tumor neo-vessels permits more macronutrients, including albumin, to leak inside the tumor area than that seen with normal tissues, implying indirect contact of the co-loaded cytotoxic species which use albumin as the template core." (PMID 34684020, 2021). "Albumin is the most abundant extracellular protein in tissues and is used as an amino acid resource in tumor cells." (PMID 33497038, 2021). "Proinflammatory cytokines such as IL1, IL6 and TNF and growth factors are released as part of the systemic inflammatory response to a tumor, affecting albumin synthesis as well as CRP secretion." (PMID 34884980, 2021). "Other occasionally reported factors included tumour distribution (peripheral or central), pneumonectomy, plasma albumin concentration, NSE concentration, C-kit protein expression, Nestin expression and EGFR mutation." (PMID 33579331, 2021). "Albumin-bound formulation reduces tumor stroma via synergy between albumin and SPARC, thereby affecting the tumor microenvironment." (PMID 34094924, 2021). "These markers (CRP and albumin) have been examined for creating risk groups of patients with DLBCL28, and the prognostic value of the CAR has also be considered based on the changing CRP and albumin levels in the tumour microenvironment." (PMID 33514832, 2021).
tumor (continued). "This is the case of [99Tc]Tc-MTHF or the [177Lu]Lu-6R-5-MTHF containing albumin binder, which showed a high tumor-to-kidney ratio compared to 177Lu-labeled folic acid conjugates containing albumin binder." (PMID 35056911, 2021). "Albumin with effective hydrodynamic diameter of 7.2 nm and long circulation is a suitable candidate for drug delivery to tumor tissues and EPR mechanism is one of the mechanisms to increase harvesting." (PMID 34051806, 2021). "We evaluated the relationship between PFS periods and serum tumor marker levels as well as biochemical indexes, including albumin, total bilirubin, and Child–Pugh scores." (PMID 33562238, 2021). "The characteristics such as tumor burden, sex, body weight, and albumin levels can modify the clearance." (PMID 34299401, 2021). "This is due to many factors that lead to a preferable accumulation of the albumin structures in the tumor." (PMID 34298666, 2021). "Secondly, the Gp60 receptor on endothelial cells is responsible for the transcytosis of albumin and aids in transporting this protein into the tumor against the efflux induced by the interstitial fluid pressure of solid tumors." (PMID 34771316, 2021). "Inflammatory cytokines surge as tumor cells progress, contributing to the suppression of albumin synthesis, albumin degradation, and the capillary escape of albumin." (PMID 34836339, 2021). "Multivariable analysis results suggest that tumor stage, ECOG performance status, ADL, serum albumin levels, BMI, and hemoglobin levels are independent risk factors of early death." (PMID 33920250, 2021). "In the univariate survival analysis, tumor size, portal vein invasion, extrahepatic spread, ALBI, AFP, AST, albumin, NLR, PLR and AST/ALT ratio were associated with OS (p < 0.05 for all)." (PMID 34124139, 2021). "Avasimin (human albumin-capsulated avasimibe) specifically induces tumor apoptosis in a tumor xenograft model." (PMID 33530546, 2021). "The tumoral uptake of albumin is enhanced by various factors, for instance, the higher concentration of albumin in blood than in the interstitial compartments allows the diffusion of albumin to tumor sites." (PMID 34208533, 2021). "The high affinity and specificity of antibodies can be exploited to improve the targeting of different nanocarriers, including albumin-based ones, for tumor cells." (PMID 34298666, 2021). "The present study exploits atovaquone/albumin nanoparticles to improve bioavailability and tumor targeting of atovaquone, enhancing the efficacy of anti-PD-1 therapy by normalizing tumor hypoxia." (PMID 34600560, 2021). "All differentiation markers (CYP3A4, HNF4α and albumin) in infigratinib‐treated FGFR‐dependent tumours were significantly increased compared with their levels in vehicle‐treated tumours." (PMID 33179425, 2021). "Accumulation of albumin in solid tumors as well as overexpression of SR-B1 in most malignancies warrant developing carrier-based drug delivery systems for tumor targeting." (PMID 34603049, 2021). "Human serum albumin (HSA) is a versatile drug carrier with active tumor targeting capacity for an antitumor drug delivery system." (PMID 34452170, 2021). "High Arg-1 expression levels were associated with male (P = 0.043), HBV infection (P = 0.022), albumin levels over 35g/L (P = 0.018), and tumor size ≥ 5 cm (P = 0.047)." (PMID 34715880, 2021). "the PTX of paclitaxel albumin nanoparticles was almost stored in the liver and kidney, and the concentration of it for which in the tumor site was relatively little, and the drug concentration gradually decreased with time." (PMID 34109887, 2021). "To further stratify our data into key clinical parameters that affected HCC TGR, we developed a tree model of the predictors that included age, sex, era, AFP, albumin, CP score, receipt of surveillance, and initial tumor size in the entire 191 HCC TGR cohort." (PMID 34966854, 2021).
tumor (continued). "PPa-SH was then bound to endogenous albumin, which afforded prolonged retention in tumours, more efficient 1O2 generation for PDT, and consequently more efficient ablation of tumours." (PMID 34522208, 2021). "Pro-inflammatory cytokines such as interleukin-1, interleukin-6, tumor necrosis factor α, are not only important impact factors for albumin production, but also critical in oncogenesis, angiogenesis and tumor progression." (PMID 33596518, 2021). "For this reason, several approaches explore the use of albumin-based NPs for encapsulating Dox and increase the selective targeting to the tumor sites." (PMID 34208533, 2021). "Second, albumin trapped within a tumor is slowly digested due to the impaired lymphatic drainage which can lead to efficient targeting or effective binding of the co-loaded species with the targeted receptor." (PMID 34684020, 2021). "Albumin decreased with R-ketorolac treatment compared to placebo resulting in values similar to non-tumor bearing control mice and near the reference range." (PMID 33413202, 2021). "In vivo, GLSF alone or in combination with abraxane (nanoparticle albumin bound paclitaxel or nab-paclitaxel) induced tumor growth inhibition and apoptosis." (PMID 35692861, 2021). "Smaller but still potentially relevant effects were observed for sex and platelet count for CL, and sex, albumin, and tumor type for V2." (PMID 33145616, 2021). "A univariate analysis demonstrated that tumor location, pathological type, tumor depth, tumor stage, FVC, MVV, total protein, and albumin were associated with prognosis." (PMID 34011041, 2021). "Multivariate analysis was performed using three variables (tumor location, serum albumin levels, and second‐line chemotherapy)." (PMID 34124386, 2021). "Albumin has been shown to accumulate within the tumor environment or inflamed tissues by receptor-mediated active transport as well as passive transport." (PMID 34064598, 2021). "In univariate analysis, WHO PS ≥ 1, tumor stage IV, the presence of active brain metastases, ≥2 metastatic sites, ≥1 prior therapies, ALB < LLN, LDH ≥ ULN, CRP ≥ 2ULN, ALC < 750/mm3, and NLR ≥ 5 were associated with worse PFS (p ≤ 0.039)." (PMID 33418936, 2021). "When the patient's body is stimulated by tumor cells and inflammatory factors, the ability of the liver to synthesize albumin is significantly reduced, and the content of serum albumin will be significantly reduced." (PMID 34840628, 2021). "Other factors correlated with poor survival were longer tumor length, lower serum albumin, left thoracotomy, palliative resection, advanced pT category, advanced pN category, advanced pTNM stage, and multiple primary malignancies." (PMID 34868958, 2021). "Albumin, which was broadly expressed by hepatocytes, clearly distinguished the tumour cells and hepatocytes." (PMID 34021647, 2021). "This is achieved due to albumin’s interaction with specific receptors overexpressed in cancerous cells, which helps to specifically deliver albumin-bound molecules to tumor cells." (PMID 34770947, 2021). "The serum albumin-based nanovehicles is one type of efficient drug delivery vehicles, which utilize serum albumin as the well-behaved carrier materials to encapsulate or conjugate the therapeutic agents for tumor-targeted drug delivery." (PMID 34869202, 2021). "In order to successfully develop tumor-specific 1-MDT-releasingprodrugs, new complexes with enhanced stability and albumin-bindingproperties are required to achieve high tumor accumulation and anticanceractivity." (PMID 34403254, 2021). "It seems that extensive surgery and a lower albumin level, when related with neoplastic disease, results in aberrant wound healing that is related with secondary infection." (PMID 34677276, 2021).
tumor (continued). "Propensity score matching was performed for performance status, albumin, number of active tumors, primary tumor site, and liver metastasis, finding higher EQD2 to remain significantly associated with improved survival within the matched cohort (p = 0.004)." (PMID 34595844, 2021). "Subsequently, BCLC stage, Child–Pugh class, maximum tumor diameter, proximity to a large vessel, and albumin (all P < 0.05) were entered into Cox proportion hazards models." (PMID 33386449, 2021). "The aim of this work was the development of new albumin nanoformulations in order to allow a more efficient intracellular delivery of doxorubicin within the tumor context and overcome cancer multidrug-resistance." (PMID 35582009, 2021). "In this strategy, 131I-labeled albumin-encapsulated liposomes, a β-ray emitting agent, facilitated tumor blood vascular permeability, resulting in an enhanced passive tumor accumulation of subsequently administered macromolecules." (PMID 33810483, 2021). "The chemotherapeutic water-soluble drug pemetrexed (PMT) was conjugated, through a tumor-cleavable bond, to the albumin backbone for specific release into the tumor." (PMID 34680176, 2021). "Yang group reported that the tumor accumulation and retention much of human serum albumin nanoparticle can significantly improve by X-rays exposure of the tumor." (PMID 34039369, 2021). "This is consistent with other macromolecule delivery systems, such as the albumin-paclitaxel conjugate Abraxane, which also utilizes endogenous transport pathways to achieve enhanced tumor tissue distribution." (PMID 34141613, 2021). "Using albumin as tumor-targeting nanoparticles to achieve photodynamic/chemotherapy combined targeted tumor therapy HAS (human serum albumin) was pre-modified with light-sensitive molecules and tumor-targeting peptides." (PMID 34425823, 2021). "The extensive investigation of albumin in cancer therapy is due to the several factors that lead to its preferable accumulation in tumor cells." (PMID 34771316, 2021). "In a model of colorectal cancer in mice, PEGylated BCZ-loaded albumin nanoparticles reduced the tumor growth, metabolic tumor volume, and total glycolysis in comparison with BCZ in solution and control groups." (PMID 34299401, 2021). "Accordingly, after the GBC2 patient received neoadjuvant chemotherapy of gemcitabine plus albumin-bound paclitaxel plus tislelizumab for 12 cycles, the size of tumor decreased by approximately 40%, indicating a partial response to the treatment." (PMID 34600546, 2021). "Worthy of note is the FDA approval of Abraxane® in 2005, which is a paclitaxel albumin-bound nanoparticle formulation for the treatment of metastatic breast cancer, showing a significantly longer time prior to tumor progression with respect to the free drug." (PMID 35582009, 2021). "We found that serum albumin concentration, tumor diameter, tumor stage, degree of differentiation, PNI, and NLR were independent prognostic factors for overall survival (OS)." (PMID 35155212, 2021). "The biguanide and ursodeoxycholic acid dual-modified multifunctional albumin were synthesized to enhance the antitumor effect and tumor-targeting efficiency." (PMID 35011278, 2021). "Tumor size (HR = 0.271, p = 0.013), ALB (HR = 0.156, p = 0.014), ALT (HR = 0.271, p = 0.017), and TBil (HR = 0.213, p = 0.016) also showed significance with OS." (PMID 34403527, 2021). "In this work we have engineered a panel of BiTE-like albumin fusions with extended circulatory half-life programmed by the FcRn affinity of the albumin sequence that exhibit improved anti-tumour effects in a beyond state-of-the-art animal model." (PMID 33686177, 2021). "The previous study has shown that only bilirubin and albumin level as non-tumor-related factors impact on survival." (PMID 34229698, 2021).
tumor (continued). "We also found that elevated INR was correlated with poor tumor differentiation, decreased level of ALB, and abnormalities in other coagulation indices, including PT, PTA, APTT, and APTT-R." (PMID 34433454, 2021). "With nanoparticles, such as liposomes, bovine serum albumin, and polymers, the radiosensitizing drugs can be promoted to reach the tumor sites, thereby enhancing anti-tumor responses." (PMID 34834172, 2021). "] accumulate in tumor tissue both through passive targeting and through active activation targeting, and therefore albumin nanoparticles have a high therapeutic ability." (PMID 34051806, 2021). "This superior accumulation of albumin-encapsulated liposomes into the tumor is thought to contribute to the high antitumor and anti-inflammatory efficacies of these systems." (PMID 33810483, 2021). "Of those other predictors, we identified that AFP of > 169 ng/mL followed by an initial tumor size of 1.8 cm and an albumin threshold of 3.6 g/dL were the best discriminators of “slow” vs. “fast” TGR." (PMID 34966854, 2021). "The optimal cut-offs were determined to be 5.25 for tumor size, 6.17 for leukocytes, 3.31 for neutrophils, 125.1 for hemoglobin, 3.31 for fibrinogen, 40.1 for albumin, 29.2 for globulin, 243 for platelets, 1.6 for NLR, and 133 for PLR." (PMID 33997045, 2021). "Considering the clinical success of albumin-mediated drug delivery to improve the pharmacokinetics and tumor targeting of drugs as well as ongoing pipelines like Al-ProD will further move albumin-binding drugs from bench to bedside." (PMID 35056979, 2021). "Here, our study has provided useful information that ALB, CEA and Ki67 as well as tumor location are associated with the risk of LNM in G-NET." (PMID 33789664, 2021). "Univariate survival analysis identified age, smoking history, tumor size, pT status, pN status, NLR, PLR, fibrinogen, albumin, AFR, and AGR as factors associated with overall survival." (PMID 34234871, 2021). "Anticancer drugs bound to human serum albumin (HSA) often benefit from significant advantages, including longer circulatory half-lives, tumor targeted delivery, and easier administration relative to the drug alone." (PMID 34163845, 2021). "Albumin nanoparticles loaded with plasmids have shown anti-tumor efficacy in various cancers, including breast, pancreatic, brain, and lung." (PMID 34298666, 2021). "Other factors known to influence survival are preoperative hemoglobin and albumin levels, location of the tumor, and preoperative comorbid conditions." (PMID 34247257, 2021). "The differences between the two anastomotic techniques underscored the heterogeneity of patient baseline characteristics which mainly showed in age, preoperative albumin level, to tumor location and tumor size with significant differences." (PMID 34976807, 2021). "Variables were related with the geriatric assessment (nutritional status and functional capabilities), the tumor itself, and with some analytical features (hemoglobin and albumin)." (PMID 33920250, 2021). "Compared with other preparations, the dual targeting of Nab-PTX-PA prodrug and albumin also improved the anti-tumor activity and survival rate of animals." (PMID 34109887, 2021). "Multivariate analysis revealed that the TNM stage, tumor site, tumor size, tumor differentiation, albumin (ALB) and aspartate aminotransferase (AST) levels, and TTR time were the seven independent prognostic factors for PRS (P < 0.05)." (PMID 33842361, 2021). "This review also highlights various approaches for the modification of the surface of albumin to enhance its transfection efficiency and targeted delivery in the tumor sites." (PMID 34298666, 2021). "A wide range of studies on albumin nanocarriers have been conducted to efficiently deliver various genetic materials to the tumor sites." (PMID 34298666, 2021).